FOXM1 (forkhead box M1)
Diseases named in the same sentence as FOXM1 in open-access papers (continued):
Sharing a sentence is not in itself a finding about the gene and the disease.
lung cancer (120 papers, 2009 to 2025). A malignant neoplasm involving the lung. "Meanwhile, circ-FOXM1 deficiency suppressed lung cancer progression by blocking the expression of miR-149-5p." (PMID 38245591, 2024). "Activation of YAP and FOXM1 axis induced EMT-associated EGFR-TKI resistance in lung cancer by dysregulating mitosis." (PMID 34322664, 2021). "FOXM1 was reported to be upregulated in lung cancer (including NSCLC) and was associated with poor prognosis of patients, as well as regulating cell proliferation, apoptosis, and metastasis of cancer cells." (PMID 34435140, 2021). "FOXM1 promotes the EMT process in lung cancer by directly activating the promoter of the EMT-associated transcriptional factors Snail, Twist and Slug." (PMID 30992007, 2019). "Taken together, these results suggest that the abnormal transactivation of FOXM1 is associated with lung cancer initiation and progression." (PMID 30992007, 2019). "FOXM1 is a promising candidate for use as a diagnostic biomarker and treatment target in lung cancer." (PMID 30992007, 2019). "Previous studies demonstrated that overexpression of FOXM1 is associated with tumorigenesis, apoptosis and progression in a variety of human cancers, specifically lung cancer." (PMID 29552057, 2017). "Previously, it has also been reported in lung cancer that transcriptional depletion of FoxM1 expression can cause reduced Cox-2 expression and on the other hand, induced over-expression of FoxM1 protein can increase Cox-2 promoter activity." (PMID 26159723, 2015). "Additionally, abnormal upregulation of FOXM1 is associated with poor clinical outcomes for patients with lung cancer." (PMID 30992007, 2019). "Overexpression of FOXM1 is associated with poor prognosis of lung cancer patients." (PMID 29228593, 2017). "We therefore hypothesized that there is a tight link between overexpression of FOXM1 and the possibility of increased risk of lung cancer among SM-injured patients." (PMID 29552057, 2017). "Increased CHK1/2 activity by Tax during S phase restricts the CDK-dependent phosphorylation of FOXM1, preventing the premature expression of G2/M genes, including those encoding cyclin-dependent kinase 4, cyclin B1, and cyclin A2, all common DEGs in lung cancer." (PMID 39228892, 2024). "Notably, the deregulation (i.e., aberrant upregulation) of FOXM1 has been reported to be a key driver of neo-oncogenesis and cancer progression, and was found to be associated with poor prognosis in several human malignancies, including lung cancer." (PMID 35743223, 2022). "The expression of FOXM1 is increased in response to high levels of reactive oxygen species (ROS) induced by sulfur mustard (SM) and may be associated with an increased risk of lung cancer among SM-exposed patients." (PMID 30992007, 2019). "Moreover, cells with the presence of the WT KRAS allele together with mutant KRAS were sensitive towards the FoxM1 inhibitor siomycin, suggesting that the targeting of FoxM1 could be a therapeutic approach in the treatment of lung cancer with both the WT and mutant KRAS alleles." (PMID 41294676, 2025). "High expression of transcription factors FOXM1, MYBL2, and UBE2C was associated with better survival in colon cancer patients, yet showed the opposite effect in stomach and lung cancers, aligning with our findings." (PMID 39542983, 2024). "FBXO22 is aberrantly highly expressed in lung cancer and participates in radioresistance formation by activating the FOXM1/Rad51 axis." (PMID 38296976, 2024). "FOXM1 expression has been shown to increase resistance to radiotherapy in lung cancer cells (A549 and H1299) by inducing kinesin family member 20 (KIF20A), a member of the Hedgehog (Hh) cascade signaling associated with tumor progression and metastasis." (PMID 39594778, 2024). "Mechanistically, FBXO22 promoted Rad51 gene transcription by increasing the level of FOXM1 at the Rad51 promoter, thereby inducing the formation of lung cancer radioresistance." (PMID 38296976, 2024).
lung cancer (continued). "The global transcriptomic network analysis highlighted the impact of five TFs, SOX4, TCF3, TEAD4, ETV4, and FOXM1, in gut and lung cancer." (PMID 39228892, 2024). "In summary, FBXO22 increases the expression of Rad51 in a FOXM1-dependent manner, which in turn triggers lung cancer radioresistance." (PMID 38296976, 2024). "Inhibition of FOXM1 has been shown to reduce the invasion of mucinous adenocarcinoma lung cancer cells." (PMID 39594778, 2024). "Mechanistically, FBXO22 promoted Rad51 gene transcription by increasing the level of FOXM1 at the Rad51 promoter, which contributes to insensitivity to lung cancer radiotherapy." (PMID 38296976, 2024). "To confirm this conjecture, we designed wild-type and mutant luciferase reporter plasmids based on the binding site of FOXM1 to the Rad51 promoter and detected the luciferase activity after co-transfecting them with siRNA targeting FOXM1 in lung cancer cells." (PMID 38296976, 2024). "Collectively, FBXO22 increases the level of FOXM1 at the Rad51 promoter, which in turn enhances the transcriptional activity of Rad51 and ultimately leads to lung cancer radioresistance." (PMID 38296976, 2024). "Collectively, our results illustrate that FBXO22 induces lung cancer radioresistance by activating the FOXM1/Rad51 axis and provide preclinical evidence for the clinical translation of this critical target." (PMID 38296976, 2024). "Mechanistically, FBXO22 facilitated transcriptional activation of the homologous recombinase Rad51 through upregulation of the transcription factor FOXM1, thus promoting DNA damage repair and lung cancer radioresistance." (PMID 38296976, 2024). "FOXM1 is overregulated in nine lung cancer datasets and is related to: 1) the negative regulation of transcription along with E2F1, FOXE1, and HMGA1; 2) cellular senescence along with E2F1, E2F3, and MYBL2; and 3) DNA repair and damage." (PMID 39228892, 2024). "Pharmacological inhibition of the MET/AKT axis reduces FOXM1 levels in lung adenocarcinoma cells, suggesting that MET/AKT is a critical target for inhibiting FOXM1 in lung cancer." (PMID 39594778, 2024). "Previous studies have shown that FOXM1 is important for regulating various processes involved in lung cancer tumorigenesis, including cell cycle progression, cancer therapy resistance, and metastasis." (PMID 38555384, 2024). "For example, FOXM1 plays a role in regulating the radiosensitivity of lung cancer cells, partially through the upregulation of KIF20A33, and FOXM1 activation leads to the progression of lung adenomas into invasive mucinous adenocarcinomas by activating AGR234." (PMID 38555384, 2024). "The KM plot analysis showed that the overregulation of three oncogenes (SOX4, BZW2, and FOXM1) as well the downregulation of four tumor suppressors (SOX17, ZBTB16, TAL1, and KLF4) is associated with worse overall survival (OS) for lung cancer patients." (PMID 36661515, 2023). "FOXM1 has critical roles in regulated tumorigenesis and malignant progression in lung cancer, including cancer therapy resistance, metastasis, and cell cycle progression." (PMID 37904848, 2023). "A recent study demonstrated that the upregulation of FOXM1 was associated with a poor prognosis among patients with HCC, colorectal cancer, and lung cancer." (PMID 35887129, 2022). "The result showed that the correlation coefficient between STIL and CCND1 was − 0.217, suggesting the strong correlation of STIL and FOXM1 is unique in lung cancer." (PMID 35365182, 2022). "Compared with other FOX family genes, FOXM1 is significantly higher in these two types of lung cancer." (PMID 36292640, 2022). "RUNX2 is also a coregulator of FOXM1, the TF that regulates all LC CCPs, thereby suggesting that RUNX2 is associated with lung cancer development, as it participates in the regulation of important genes coexpressed in several lung cancer networks." (PMID 36551878, 2022).
lung cancer (continued). "The inhibition of MELK also decreases its downstream forkhead box protein M1 (FOXM1) activation and Akt expression in lung cancer cells, leading to apoptosis of NSCLC cells." (PMID 36467499, 2022). "CircTP63 increases the proliferation of lung cancer cells by sponging miR-873-3p and upregulating FOXM1-related pathway." (PMID 35365208, 2022). "This miRNA was also reported to inhibit the growth and aggressiveness of human lung cancer through a FOXM1/cyclin D1/MMP2 axis." (PMID 35129056, 2022). "SH3PXD2A-AS1 regulates the expression of FOXM1 by binding to DHX9 in lung cancer cells to promote cell proliferation and cell cycle progression." (PMID 35410446, 2022). "Based on the fact that knockdown of CBX3 results in an upregulation of FBP1 in pancreatic cells and upregulation of FOXM1 results in a decrease in FBP1 expression in lung cancer, it seems the simulation is indeed correct." (PMID 35404841, 2022). "RUNX2 also acts as a coregulator of FOXM1, the TF that regulates lung cancer CCPs, and RUNX1, a TF that is coexpressed in the networks of unique lung cancer genes that are not deregulated in other lung diseases (LCI) or other types of cancer (LCII)." (PMID 36551878, 2022). "A significant decrease in PD‐L1 levels was observed, revealing the dual role of FOXM1 in regulating the proliferation as well as the immune evasion of lung cancer cells." (PMID 35975458, 2022). "We immunostained tumor tissues from lung cancer tissues with antibodies against FOXM1 and PD‐L1, and compared the expression of FOXM1 and PD‐L1 to their corresponding normal counterparts." (PMID 35975458, 2022). "For instance, Pro destroys AG in lung cancer (LC) via modulating the circTADA2A/miR-455-3p/FOXM1 axis." (PMID 35543376, 2022). "We also highlighted the potency of TST, a FOXM1 inhibitor, in reducing the proliferation of lung cancer cells and the expression of PD‐L1 through FOXM1 inhibition." (PMID 35975458, 2022). "We also provided insights into how MYBL2, FOXM1, and cell-cycle genes, which are critical for lung cancer patient survival, are regulated in lung adenocarcinoma cells." (PMID 36291764, 2022). "First, CENPE is overexpressed in lung adenocarcinoma and promotes lung cancer cells proliferation, which is regulated by FOXM1." (PMID 34944924, 2021). "In vitro studies further determined that the pro-proliferative effect of CENPE expression on lung cancer cells is modulated directly by FOXM1 via binding to the promoter region of CENPE." (PMID 34868981, 2021). "Data from two studies showed that circRNAs upregulated in lung cancer tissue and cells, promoted lung cancer progression by regulating FOXM1 via miRNA sponging." (PMID 34295810, 2021). "Combined use of TNF-α and TGF-β can promote the dryness of H460 lung cancer through NF-κB and FoxM1 pathways." (PMID 35069596, 2021). "FOXM1 was suggested as a potential biomarker for resistant lung cancers and its presence predicted a worse clinical outcome." (PMID 34322664, 2021). "In most cancers, including lung cancer, FOXM1 is oncogenic in nature thanks to its repeated upregulation, thereby generating a poor prognosis for patients." (PMID 34295810, 2021). "Formerly, there is also a former study confirmed that FOXM1 cannot affect ZEB2 promoter transcription in lung cancer cells." (PMID 32513952, 2020). "Previous studies had implicated FOXM1 and MYBL2 in lung cancer, but our analysis documents their profound effects on gene deregulation, potentially affecting hundreds of enhancers." (PMID 32925947, 2020). "FOXM1 and MYBL2 motifs were enriched at CENPA, FOXM1, and MYBL2-linked enhancers we found in lung cancer cells (91.8% for a FOXM1 motif, 60.3% for an MYBL2 motif)." (PMID 32925947, 2020). "FOXM1 has been identified to be upregulated in lung cancer and is critical for the tumorigenicity of malignant lung cells, making it a new target for cancer diagnosis and therapies." (PMID 32514270, 2020).
lung cancer (continued). "In lung cancer, circTP63 functions as a ceRNA to upregulate FOXM1 expression and promote cancer progression." (PMID 32979257, 2020). "Here, we demonstrate that FAM188B influences cell growth by regulating FOXM1 protein levels in lung cancer cell lines." (PMID 33142744, 2020). "Several studies have demonstrated that numerous oncogenic stimuli that initiate different signaling cascades ultimately converge on a common program targeting FOXM1 transcription factor activity, resulting in the upregulation of FOXM1 in lung cancer." (PMID 30992007, 2019). "It has been reported that FOXM1 can enhance the radioresistance of lung cancer by inducing the expression of KIF20A." (PMID 31093305, 2019). "(iv) FOXM1 is frequently upregulated in 22 human malignancies, including lung cancer, and the FOXM1 regulatory network is a major predictor of poor outcomes." (PMID 30992007, 2019). "In summary, FOXM1 expression is increased in lung cancer tissues with different histological subtypes at the mRNA and protein levels." (PMID 30992007, 2019). "FOXM1 mRNA data related to lung cancer were retrieved from the Oncomine database, and 19 studies involved the FOXM1 mRNA profiles in lung cancer tissues and normal tissues, including 1197 clinical samples in total." (PMID 30992007, 2019). "FOXM1 functions downstream of oncogenic Kras and is required for its induction of lung cancer formation." (PMID 30992007, 2019). "Special attention must be paid before FOXM1 can be translated into a specific therapeutic target for lung cancer patients." (PMID 30992007, 2019). "Current evidence supports that FOXM1 functions as an attractive chemotherapeutic target involved in DNA damage repair, cell apoptosis signals, and CSCs of various cancers, including lung cancer." (PMID 30992007, 2019). "In summary, FOXM1 is overexpressed in cancer cells resistant to TKIs (including sorafenib and gefitinib), NVB, docetaxel, cisplatin and radiation, and inhibiting the expression of FOXM1 is a promising method for lowering resistance to lung cancer treatment." (PMID 30992007, 2019). "A previous study showed that patients with stage I lung cancer who smoked or were greater than 55 years of age, strong FOXM1 expression had a substantially higher recurrence rate than those with weak/negative FOXM1 expression." (PMID 30992007, 2019). "Tyrosine kinase inhibitors (TKIs) contribute to the aberrant activation of the AKT/FOXM1 pathway during the lung cancer treatment process." (PMID 30992007, 2019). "FOXM1 is required for the Kras-induced formation of lung cancer by activating genes critical for the nuclear factor-kB (NF-kB) and c-Jun N-terminal kinase (JNK) pathways, such as Ikbkb, Nfkb1, Nfkb2, Rela, Jnk1, N-Myc, Pttg1 and Cdkn2a." (PMID 30992007, 2019). "MiR-342 was shown to be a negative regulator of E2F1 affecting MYC expression in lung cancer cells and also negatively regulate FOXM1 and FOXQ1 expression in colorectal cancer cells." (PMID 29599914, 2018). "Another study from Hou elucidated that overexpression of miR-361-5p suppressed lung cancer proliferation and invasion by targeting FOXM1." (PMID 29435149, 2018). "To examine the role of FOXM1 in pulmonary carcinogenesis, we used a urethane-induced lung cancer model." (PMID 29267283, 2017). "We considered the expression of Forkhead box M1 (FOXM1) and apolipoprotein E (APOE) genes, which are responsible for cell proliferation, differentiation, tumorigenesis, and increased risk of lung cancer, in the lung bronchial tissue of patients exposed to SM." (PMID 29552057, 2017). "FOXM1 is a transcription factor, which is induced in lung cancers and is correlated with poor prognosis." (PMID 29267283, 2017).
lung cancer (continued). "Mustard lungs were associated with increased expression of FOXM1 and APOE genes, which suggests an increased risk of lung cancer among these patients." (PMID 29552057, 2017). "FoxM1 gene is widely described as amplified also in lung cancer, regulating cell proliferation by promoting both G1/S and G2/M transition, differentiation, and transformation as well as inhibition of apoptosis." (PMID 28770020, 2017). "More recent studies have considered the FOXM1 as a novel biomarker of lung cancer because not only it stimulates proliferation and growth of cells, but also it is associated with high DNA replication rates of lung tumor cells." (PMID 29552057, 2017). "In humans, increased FOXM1 was correlated with higher grades of lung cancers and poor patient survival." (PMID 29267283, 2017). "SRPX2 and FOXM1 were proven to be directly regulated by mir-149 in colorectal cancer and lung cancer, respectively." (PMID 25405731, 2014). "Accordingly, a lung tumorigenesis study demonstrated that overexpression of FOXM1 promoted Clara cell hyperplasia and cooperated with activated K-Ras to induce lung cancer development in vivo." (PMID 24325450, 2013). "Expression of Foxm1 in respiratory epithelial cells is critical for lung cancer formation and TOPO-2α expression in vivo, suggesting that Foxm1 is a promising target for anti-tumor therapy." (PMID 19672312, 2009). "The important contribution of the current study is the establishment of the critical role of Foxm1 in respiratory epithelial cells during formation of lung cancer." (PMID 19672312, 2009). "Our studies suggest that Foxm1 represents a potential therapeutic target in treatment of NSCLC lung cancers." (PMID 19672312, 2009). "In the present study, transgenic mice were generated in which the Foxm1 gene was conditionally deleted in lung epithelial cells (epFoxm1−/− mice) either prior to the initiation of chemically-induced lung cancer, or during cancer progression/expansion." (PMID 19672312, 2009). "Taken together, our data demonstrate that Foxm1 expression in respiratory epithelial cells is critical for expansion of lung cancer and TOPO-2α expression in lung tumor cells." (PMID 19672312, 2009). "Altogether, these observations provide new insight into a cell autonomous role of Foxm1 in the pathogenesis of pulmonary adenocarcinoma, and identify the Foxm1 transcription factor as a potential target for treatment of human lung cancer." (PMID 19672312, 2009). "TNFRSF21 (DR6) is a receptor involved in regulating the immune response that contributes to malignant survival, promoting tumor aggressiveness in lung cancer by increasing ERK/FOXM1 signaling, and cancer stem cell characteristics by promoting CD133 and CD44 mRNA expression." (PMID 41440381, 2025). "Therefore, we conclude that FBXO22 upregulates the expression of FOXM1 and FOXM1 directly binds to the Rad51 promoter to transactivate Rad51, which ultimately leads to lung cancer radioresistance." (PMID 38296976, 2024). "AKT/FOXM1/STMN1 axis in lung cancer also contributes to resistance to tyrosine kinase inhibitors." (PMID 38698443, 2024). "MIAT can target the miR-149-5p/FOXM1 axis to regulate lung cancer progression partially." (PMID 38095636, 2023). "FOXM1 has also been found to recruit macrophage migration in FOXM1 in lung cancer." (PMID 37234166, 2023). "In summary, we confirmed that STAT3/FOXM1/ATG7 signalling might be essential for autophagy induced by icotinib in resistant lung cancer cells." (PMID 35690866, 2022). "We also analyzed the related cell functions of FOXM1 in lung cancer cells." (PMID 36435510, 2022). "A new model for FOXM1‐mediated regulation of PD‐L1 expression in lung cancer was proposed." (PMID 35975458, 2022). "In addition, we performed functional studies on LUAD cell A549 to preliminarily evaluate the role of FOXM1 in lung cancer." (PMID 36435510, 2022).